IFI27 (interferon alpha inducible protein 27)
Diseases named in the same sentence as IFI27 in open-access papers (continued):
Sharing a sentence is not in itself a finding about the gene and the disease.
COVID-19 (60 papers, 2020 to 2025). A disease caused by infection with severe acute respiratory syndrome coronavirus 2. "It has been reported that the expression of IFI27 was found in the respiratory tract of COVID-19 patients, and an elevated IFI27 expression in the lower respiratory tract was associated with higher viral load." (PMID 41081508, 2025). "An observational multi-cohort study found that IFI27 is highly expressed in the lower respiratory airways of COVID-19 patients and is associated with the presence of a high viral load." (PMID 37638007, 2023). "The findings provided herein represent the first evidence that IFI27 expression has a potential as a blood biomarker for risk stratification in COVID-19 patients." (PMID 36685600, 2022). "Here, we have provided the first evidence of blood IFI27 expression as a potential biomarker for risk stratification of COVID-19 patients." (PMID 36685600, 2022). "Importantly, we observed a stronger association between COVID-19 outcome and the IFI27 gene expression than that observed with the IFI27 protein expression in blood." (PMID 36685600, 2022). "The up-regulation of IFI27 associates with COVID-19 symptomatic infection, which was confirmed by recent studies, but whether the down-regulation of TUBB2A associates with similar clinical scenario requires further confirmation." (PMID 34554255, 2022). "Accordingly, the strong association observed between IFI27 upregulation and severe COVID-19 could be indicative of an increased viral replication." (PMID 36685600, 2022). "In a multi-cohort study, IFI27 transcription was identified as an early predictor for the outcome of COVID-19 patients." (PMID 40055791, 2025). "Five genes, including PAFAH2, LINC02915, CLSPN, EIF4G1 and IFI27, were predictors of both COVID-19 and RSV-LRTI hospitalization." (PMID 41279033, 2025). "The top upregulated genes included known genes responsible for immune responses, such as Interferon alpha-inducible protein 27 (IFI27) which is known to be an early predictor for COVID-19 outcome." (PMID 41279033, 2025). "A single-center cohort study comparing peripheral blood transcriptomes at one time point showed IFI27 was highly upregulated in COVID-19, even when compared to influenza and seasonal coronaviridae." (PMID 39161760, 2024). "Despite the sparsity in single cell data and relatively low coverage of the IFI27 locus, in samples from patients with acute COVID-19, we found a higher number of IF27 sequencing reads in monocytes compared to all lymphocyte populations." (PMID 39616162, 2024). "This recapitulates findings of other study that suggest robust and specific upregulation of IFI27 in COVID-19." (PMID 39161760, 2024). "We observed that certain genes in the severe COVID-19 gene set, such as IFI27, HLA-DQB1, and CLU, also hold significance in the context of influenza patient classification." (PMID 39350339, 2024). "For PC2, the most contributing genes were IFI27, involved in type I interferon cell response, and OTOF, both over-expressed in COVID-19 patients and associating with the severity of evolution." (PMID 38772950, 2024). "The IFN-α-inducible protein 27 (IFI27) was the top upregulated gene in the COVID-19 cohort, which is an early predictor for the outcome of COVID-19 patients." (PMID 39625479, 2024). "Overall, this clearly demonstrated a stepwise increase of S100A12 activation in COVID-19, while IFI27 activation was similarly predominant in hospitalized COVID-19 patients irrespective of disease severity." (PMID 36649304, 2023). "In the meantime, IFI27 expression was similar in the mild, severe and critical COVID-19 patient groups (p>0.05 for pairwise comparison)." (PMID 36649304, 2023). "IFI27, interferon alpha inducible protein 27, transcription has recently been a proven predictor for COVID-19 outcomes." (PMID 37685932, 2023). "Again, activation of S100A12 was generally accompanied by the activation of IFI27 in COVID-19 patients (84.1% for this cohort)." (PMID 36649304, 2023).
COVID-19 (continued). "In the meantime, IFI27 expression was below 7.0 in all of the 17 healthy volunteers (median value 4.0), while it was above 7.0 in 15 of the 16 COVID-19 patients (median value 13.3, 10.33, and 9.98 for the moderate, severe and critical group, respectively)." (PMID 36649304, 2023). "In this study, a two-tiered innate immune response was demonstrated in COVID-19 patients, and a two-gene marker (IFI27/S100A12) for this two-tiered innate immune response was proposed." (PMID 36649304, 2023). "The infected macrophages of COVID-19 patients release large amounts of interferon into the blood, which activates mitochondrial IFI27 expression and disrupts the energy metabolism of immune cells." (PMID 36911695, 2023). "Here, we use multiple patient cohorts to evaluate the role of IFI27 expression in predicting COVID-19 disease progression." (PMID 36685600, 2022). "Only one gene directly related to the interferon response was detected in our COVID-19 specific gene signature: interferon-alpha inducible protein 27 (IFI27)." (PMID 35991542, 2022). "We conducted a multi-cohort observational study to investigate the biology and the prognostic role of interferon alpha-inducible protein 27 (IFI27) in COVID-19 patients." (PMID 36685600, 2022). "Nevertheless, we further assessed the prognostic potential of IFI27 expression in nasopharyngeal swabs of COVID-19 patients (Cohort 2; Chile)." (PMID 36685600, 2022). "Although this cohort was recruited during the peak of the Delta wave in Iran, the same trend was observed: increased IFI27 expression was observed in patients with more severe COVID-19." (PMID 36685600, 2022). "We also noted that IFI27 blood expression was high in COVID-19 patients who developed an adverse outcome." (PMID 36685600, 2022). "We show that IFI27 is expressed in the respiratory tract of COVID-19 patients and elevated IFI27 expression in the lower respiratory tract is associated with the presence of a high viral load." (PMID 36685600, 2022). "IFI27, a reported biomarker of influenza distinct from bacterial infection, was the strongest upregulated gene in patients with COVID-19 in the scRNA-seq data." (PMID 33677468, 2021). "There is a lack of robust clinical evidence concerning IFI27-related prognostic value for COVID-19; however, ISGs and, particularly, IFI27 seem to be interesting for conducting further studies." (PMID 34745112, 2021). "We performed PBMC immunofluorescence testing to compare the protein expressions of IFI27 between patients with COVID-19 and the controls." (PMID 33677468, 2021). "Immunofluorescence staining showed that IFI27 was highly expressed in the lymphocytes of patients with COVID-19 but only partially expressed in the lymphocytes of the controls." (PMID 33677468, 2021). "Recently, IFI27 has also emerged as an early predictor of coronavirus disease 2019 (COVID-19)." (PMID 41081508, 2025). "This suggests that plasma cells may be a large contributor to high IFI27 expression in COVID-19 patient blood." (PMID 38580667, 2024). "Notably, during the treatment of COVID-19, the down-regulation of genes like IFI27, which possesses antiviral effects and activates neutrophils, aligns with the increased inflammatory response observed in these patients." (PMID 38601162, 2024). "Furthermore, IFI27 expression is upregulated in the blood of SARS-CoV-2 positive patients, and IFI27 is upregulated in the respiratory tract of COVID-19 patients." (PMID 39431052, 2024). "Moreover, decreased interferon alpha inducible protein 27 levels were observed in COVID-19 patients with higher miR-146a-5p levels." (PMID 38543491, 2024). "Genes such as IFI27 that exert antiviral effects and neutrophil activation are downregulated during treatment in COVID-19 patients, which is consistent with the dynamically enhanced inflammatory response of COVID-19 patients." (PMID 36911695, 2023).
COVID-19 (continued). "IFI27, which may serve as an early transcriptomic biomarker in the blood samples obtained from COVID-19 patients, was upregulated in alveolar and vascular regions, particularly with a significantly high fold-change in vascular ROIs." (PMID 37640792, 2023). "Among prominent ones are CXCL10, a marker of acute viral infection, ISG15, both an extracellular cytokine and an intracellular protein modifier, IFI6 that may be involved in the regulation of cell apoptosis and IFI27, a proven predictor for COVID-19 outcomes." (PMID 37685932, 2023). "The upregulation of IFI27 expression in blood could be a predictor of respiratory failure in COVID-19 patients." (PMID 37638007, 2023). "Notably, a cohort study demonstrated that IFI27 expression was observed in the blood of COVID-19 patients and positively correlated with elevated viral load." (PMID 37630661, 2023). "A practical question is whether the activation of IFI27 or S100A12 is correlated with COVID-19 severity." (PMID 36649304, 2023). "On the other hand, the fast waning of IFI27 activation suggests that IFI27 expression may serve as a surrogate of disease duration in patients with COVID-19." (PMID 36649304, 2023). "Inflammatory-related genes, such as ISG15 and IFI27, were upregulated in COVID-19 patients." (PMID 36732528, 2023). "Thus, we proceeded to measure IFI27 expression levels in peripheral blood of COVID-19 patients (Cohort 6; Iran)." (PMID 36685600, 2022). "IFI27 expression was negatively correlated with the naïve B cell and Treg counts and positively correlated with the plasma cell counts in the blood of patients with COVID-19." (PMID 35844544, 2022). "Therefore, the usefulness of IFI27 expression as a prognostic biomarker for COVID-19 has yet to be determined." (PMID 36685600, 2022). "We then used an independent prospective cohort (Cohort 7; Australia & Singapore) to test the hypothesis that changes in blood IFI27 gene expression could predict outcomes in COVID-19 patients." (PMID 36685600, 2022). "In addition, IFN-I signal-induced gene IFI27 mRNA levels remarkably increased in patients with COVID-19." (PMID 35928229, 2022). "Preliminary evidence suggests that IFI27 expression may be a useful biomarker for COVID-19 diagnosis." (PMID 36685600, 2022). "We first investigated whether IFI27 expression could be detected in COVID-19 patients by assessing gene expression in the lower respiratory tract of deceased COVID-19 patients (Cohort 1; Brazil; n=4)." (PMID 36685600, 2022). "IFI27 is also upregulated in the peripheral blood of COVID-19 patients and may serve as a biomarker for pre-symptomatic SARS-CoV-2 infection." (PMID 36685600, 2022). "Our study showed that IFI27 expression significantly increased in alveolar invasive macrophage subsets and blood immune cells in patients with COVID-19 and played an important role in the disproportion of peripheral blood immune cells and lung–blood interaction." (PMID 35844544, 2022). "Moreover, in another multi-cohort observational study, IFI27 was shown to be expressed in COVID-19 infected patients, and its level of expression was associated with the presence of a high viral load." (PMID 35186993, 2022). "IFI27 was consistently up-regulated in COVID-19 when compared to the healthy controls, but the comparisons against other infections and in relation to disease severity varied depending on the dataset, perhaps reflecting inconsistent interferon response observed in previous studies." (PMID 35991542, 2022). "Instead, we propose that IFI27 expression reflects increased immunopathology (either local or systemic) and could predict COVID-19 outcome." (PMID 36685600, 2022). "Indeed, some studies have suggested IFI27 expression is lowest in the critical care or ICU COVID-19 patients which is as apparently incongruent with the data presented herein." (PMID 36685600, 2022).
COVID-19 (continued). "Given that IFI27 was significantly increased in all patients with COVID-19 and FOS was dramatically decreased in recovered patients, these two markers might be used for disease condition prediction in the future." (PMID 33677468, 2021). "Moreover, another two genes, IFI27 (encoding interferon alpha-inducible protein 27, mitochondrial) and EPSTI1 (encoding epithelial-stromal interaction protein 1), have numerous strong correlations with the genes in the target pathway of COVID-19." (PMID 38096046, 2024). "Additionally, since most of the S100A12 activation is accompanied by IFI27 activation in patients with severe COVID-19, it is unlikely that the inability of ISG activation is to blame for most of the severe symptoms, which has implications in the usage of interferon as a therapeutic option." (PMID 36649304, 2023). "Notably, the IFI27 gene expression had a high sensitivity (0.95), high specificity (0.83) and an AUROC of 0.90, all of which were higher than known factors associated with COVID-19 outcomes (e.g., age, co-morbidity)." (PMID 36685600, 2022). "Using this approach, genes S100A8, IFI27, CLU, IFITM3, and MT-CO1 have been identified as the stable gene panel for the classification of severe COVID-19 patients, utilizing the same training dataset as previously employed." (PMID 39350339, 2024). "Although part of ISGs (i.e., IFI27) were enhanced in SARS-CoV-2 infection, moderate IFN responses have been a sign of COVID-19." (PMID 39066192, 2024). "Additionally, the interferon-inducible gene IFI27 is highly expressed in the respiratory tract and PBMCs of patients with COVID-19, and it may also affect the molecular mechanisms of the innate immune response through negative feedback regulation, thus facilitating viral replication." (PMID 38238762, 2024). "Overall, the stepwise increase of S100A12 activation and fast waning of IFI27 activation were consistently observed in whole blood and PBMC of patients with COVID-19." (PMID 36649304, 2023). "Subsequently, three key genes (CDKN1A, IFI27, and STAB1) were screened using machine learning to predict the occurrence of COVID-19 related IIM." (PMID 37638007, 2023). "DEG analysis revealed a common inflammatory phenotype across both HIV-1 and COVID-19 which included known IFN-I signaling genes such as IFITM3 and IFI27." (PMID 36992700, 2023). "It showed that activation of both genes can be observed in the first week of the disease course, and activation of IFI27 was more common and at larger scale than that of S100A12 in hospitalized patients with COVID-19." (PMID 36649304, 2023). "As host markers for infection, activation of both IFI27 and S100A12 was observed in a significant portion of patients with COVID-19 compared to healthy controls." (PMID 36649304, 2023). "In this study, the activation patterns of this two-tiered innate immune response represented by IFI27 and S100A12 were explored based on 1421 samples from 17 transcriptome datasets derived from the blood of COVID-19 patients and relevant controls." (PMID 36649304, 2023). "Although IFN genes such as IFI27 and IFI44L are also highly expressed in various cell types in COVID-19 samples, monocytes contributed the most among PBMCs, suggesting its active involvement in interferon response." (PMID 38268924, 2023). "Since IFI27 has been found to be upregulated in influenza, RSV and COVID-19, an effort to identify a single-gene biomarker with a high diagnostic accuracy and specificity to influenza virus in one study was attempted." (PMID 35186993, 2022). "IFI27 and IFI6 expression remained significantly elevated in COVID-19 patients likely due to an overall increase in the anti-viral response." (PMID 35477940, 2022). "Important gene combinations in the white blood cells of patients with COVID-19, including IFIT3, OASL, USP18, XAF1, IFI27, and EPSTI1, can be used for its diagnosis." (PMID 35928229, 2022).
COVID-19 (continued). "Both CUN and COV groups, compared with their respective control group, expressed higher level of genes involved in the antiviral response and proliferation, like IFIT5, IFI27 and PIM1, suggesting that those cells could have been activated by SARS-CoV-2 infection." (PMID 35710943, 2022). "This phenomenon reflects the discussions in the Introduction that RIPK3 is related to the natural essence of COVID-19, while ATP6V1B2, IFI27, BTN3A1, SERTAD4, and EPSTI1 contain more information about SARS-CoV-2." (PMID 36298522, 2022). "IFI27 was among the genes upregulated in the peripheral blood mononuclear cells (PBMC) of severe and mild COVID-19 patients, compared with two healthy controls." (PMID 34745112, 2021). "Both previously published RNA sequencing analysis of the same samples, and RT-qPCR experiments done for this project confirm that transcriptional products of IFI27 and OAS2 are upregulated in COVID-19 samples in comparison with non-COVID-19 control patients." (PMID 34034806, 2021). "Considering all COVID-19 patients, we observed increases in interferon-stimulated genes, including interferon alpha-inducible protein 6 (IFI6), interferon alpha-inducible protein 27, mitochondrial (IFI27)." (PMID 39161760, 2024). "While multiple interferon-stimulated genes showed significant upregulation in our analysis, one specific gene, interferon-inducible protein 27 (IFI27), showed significant upregulation at study enrollment in COVID-19 ARDS compared to non-COVID-19 ARDS." (PMID 39161760, 2024). "The goal of this work is to find out whether IFI27 and S100A12 can be used as effective markers to monitor COVID-19 progression." (PMID 36649304, 2023). "Notably, genes such as IFI27 and OAS1, which are involved in defense responses and apoptotic signaling, were upregulated in both PBMC and lung samples of COVID-19 patients." (PMID 38681774, 2023). "Another study found increased levels of IFI27 and OAS2 in COVID-19 patients." (PMID 37053191, 2023). "For example, IFI27 expression was above 5.0 in 6 of the 21 patients with mild COVID-19, 4 of the 17 severe COVID-19 patients without secondary infection, and one of the 5 severe COVID-19 patients with secondary infection." (PMID 36649304, 2023). "Overall, S100A12 activation was correlated with disease severity (with or without COVID-19), while IFI27 activation was more specific to COVID-19." (PMID 36649304, 2023). "When protein expression of IFI27 was measured, there were no elevation in COVID-19 patients (Cohorts 4 and 5; Chile & Brazil) and it did not correlate with disease severity." (PMID 36685600, 2022). "When prospectively validated, blood IFI27 expression showed a high positive and negative predictive value, outperforming other known predictors of COVID-19 outcomes reported in the literature." (PMID 36685600, 2022). "It is also noted that the 432 dysregulated genes, the IFI27 and TUBB2A co-expression genes were consistently enriched in the disease pathway of systemic lupus erythematosus, which was also activated in the COVID-19 patients compared with their controls." (PMID 34554255, 2022). "Genes associated with the IFN pathway, such as IFI27, IFIT1, IFIT2, OASL and OAS3, showed significantly higher expression levels, in particular individuals with long COVID-19 when compared to non-long COVID-19 and the organoid systems infected with the alpha variant." (PMID 40055791, 2025). "Genes enriched in male Mo/DCs relative to female Mo/DCs included multiple ISGs (IFI27, IFI6, and ISG15), prompting us to perform an upstream regulator analysis to identify cytokines predicted to promote sex-biased Mo/DC gene expression patterns in patients with COVID-19." (PMID 37606044, 2023). "Classical monocytes in severe COVID-19 were found to be accompanied by the IFN-I response that was characterized by the up-regulation of various interferon-stimulating genes (ISGs), including ISG15, IFITM1/2/3, ISG20, IFI27, and MX1 when compared to mild COVID-19." (PMID 36159873, 2022).